MYD88 (MYD88 innate immune signal transduction adaptor)
Diseases named in the same sentence as MYD88 in open-access papers (continued):
Sharing a sentence is not in itself a finding about the gene and the disease.
B-cell lymphomas (41 papers, 2013 to 2025). "Our PSEL-MZL exhibited a MYD88 L265P mutation, known to constitutively activate NF-κB signaling and associated with extranodal disease and inferior outcomes in various B cell lymphomas." (PMID 40993401, 2025). "Zanubrutinib is a BTK inhibitor reported to be effective for B‐cell lymphomas with MYD88 and CD79b mutations, double expression of MYC and BCL2/BCL6, and CD5 expression." (PMID 39054569, 2024). "The in vivo efficacy of emavusertib in B-cell NHL was first evaluated in an OCI-Ly3 xenograft model (xenograft model of ABC DLBCL with MYD88-L265P mutation) through once daily oral administration." (PMID 37954584, 2023). "MYD88 mutation is a widely accepted pivotal oncogenic driver in B-cell lymphomas, among which, the hotspot MYD88L265P is mostly studied." (PMID 37093346, 2023). "The discovery of the activating mutation of MYD88 (MYD88L265P being the far most frequent) in more than 90% of WM cases contributed to the concept that this entity is genetically distinct from other B-cell lymphomas." (PMID 34017329, 2021). "Pleural fluid cytology demonstrated B-cell lymphoma of the lymphoplasmacytic subtype, with monoclonal kappa B-cell population on flow and a positive MYD88 L265P mutation." (PMID 32654665, 2020). "Pleural fluid (PF) cytology was positive for malignant cells consistent with B-cell lymphoma and positive for MYD88 L265P mutation." (PMID 32654665, 2020). "The splicing variant of MyD88 in B-cell lymphoma maintains the activation of NF-κB pathway." (PMID 38690287, 2024). "Therefore, more research is required to understand other genetic and epigenetic changes that underlie the MYD88 expression found in several B-cell NHL patients." (PMID 38335426, 2024). "In addition, a recent study demonstrated the role of SYK to promote the survival of MYD88-mutated B-cell lymphoma cells in vitro." (PMID 33921415, 2021). "Beside B-cell lymphomas, where MyD88 activation is a direct promoter of carcinogenesis, dysregulation of MyD88 can have direct effects on tumour progression or indirect effects on the immune microenvironment of the tumour." (PMID 40040472, 2025). "When injected into the Prdm1.fl/Myd88/Bcl2 mice after they had developed their autochthonous B cell lymphomas, mCAR and mCAR/mCCR cells prevented tumor growth in most mice." (PMID 38340727, 2024). "Examination of alterations in key pathways implicated in B-cell lymphomas suggests involvement in chromatin remodelling (CREBBP and EP300) and regulators of NF-κB signalling (TNFAIP3, BCL10, MYD88, CD79B and CARD11) were affected." (PMID 39460552, 2024). "Persistent TLR signaling downstream of BTK and MYD88 in B-cell NHL patients treated with BTK inhibitors highlight the need to target other proteins in the TLR pathway." (PMID 37954584, 2023). "Here, we demonstrate that MYD88 S257 is phosphorylated in B-cell lymphoma cells and that this phosphorylation is required for optimal TLR-induced NF-κB activation." (PMID 37591861, 2023). "The current published mouse models with continuous MYD88 activation in the B-cell lineage develop aggressive clonal B-cell lymphomas that resemble human ABC-DLBCLs." (PMID 34017329, 2021). "We, therefore, hypothesized that senescence-prone MyD88-mutant B-cell lymphomas might represent a subgroup with intrinsic similarities to the TIS-associated aberrant phenotype switch." (PMID 40159497, 2025). "Over-activation of MyD88 is a recognized driver of carcinogenesis in B-cell lymphomas." (PMID 40040472, 2025). "who determined that the most likely etiology of ‘secondary CAD’ in a patient with lung cancer treated with pembrolizumab was a low-grade B-cell lymphoma with lymphoplasmacytic differentiation negative for the MYD88 mutation." (PMID 40677712, 2025). "Sanger sequencing further confirmed the presence of MYD88 L265P in patients with mature B-cell NHL." (PMID 38335426, 2024).
B-cell lymphomas (continued). "Our data thus provide an explanation why oncogenic mutations have only been reported in B cell lymphoma, rather than tumors arising from myeloid cells, whose MyD88s induction loop possibly renders them more resistant to MyD88 pathway induced NF-κB activity." (PMID 34163463, 2021). "Detection of MyD88 mutation supports the diagnosis of a B cell lymphoma, regardless of whether this is PVRL/CNS DLBCL or any other B cell lymphoma, and the presence of mutation essentially rules out uveitis." (PMID 35158867, 2022). "Interestingly, a gain-of-function mutation of MYD88 that promotes cell survival via activation of IL-1 receptor-associated kinase 1, nuclear factor (NF)-κB, and JAK/STAT3 signaling is frequently found in cases of a subtype of B-cell lymphoma." (PMID 24662938, 2014). "In some B-cell lymphomas, chronic BCR signaling and constitutive MYD88/TLR signaling come together on IKK culminating in NF‐κB activation." (PMID 37954584, 2023). "Knockdown of MYD88 expression has significantly inhibited secretion of IL-6 and phosphorylation of STAT3 in B-cell lymphoma cells." (PMID 24662938, 2014). "It is worthwhile to note that MyD88 mutation will not detect T cell lymphomas, a small subset of PVRL/ CNS DLBCL, and some B cell lymphomas of other types." (PMID 35158867, 2022). "In the field of oncology research, adverse effects from TLR immunotherapy have been linked to unintended expansion of adaptive leukocytes, such in B-cell lymphoma, where activation of TLR4 MyD88-dependent signaling may exacerbate the disease." (PMID 33679711, 2020). "MYD88 mutations did not co-occur with EZH2 or TNFRSF14 mutations, which are mostly found in B-cell lymphomas of the germinal center as opposed to the activated B-cell lymphomas, in which MYD88 is commonly mutated." (PMID 40511879, 2025). "However, the MYD88 L265P and PIM1 p.G28A, p.L184V, and p.V197F mutations have not yet been examined in conjunction with MYD88 and PIM1 protein expression in large B-cell NHL cases." (PMID 38335426, 2024). "Furthermore, splicing in B cell lymphomas appears to strongly favor the canonical MYD88 isoform without diverting splicing events to alternative or signaling-incompetent splice isoforms." (PMID 34163463, 2021).
Autoimmunity (38 papers, 2008 to 2025). The occurrence of an immune reaction against the organism's own cells or tissues. "Deficiency of MyD88 (an adaptor protein downstream of TLR7) rescued autoimmunity, aberrant B cell survival, and all cellular and serological phenotypes." (PMID 35477763, 2022). "T1D resistance through loss of MYD88 is attributed to disruption in the gut flora since these MYD88-KO mice develop autoimmunity when housed in germ-free facilities." (PMID 29018409, 2017). "MYD88 functions as a key adaptor molecule in innate immune signaling via toll like receptors (TLRs), and there is increasing recognition of the common signaling pathways involving nuclear factor-κB (NF-κB) for both WM and TLRs associated autoimmunity." (PMID 37245043, 2023). "Evaluation of autoimmunity in female MyD88-deficient MRL/lpr (MyD88-/- MRL/lpr) mice at 24 weeks of age revealed reduced severity of salivary gland inflammation and serum titers of anti-dsDNA autoantibodies, as well decreased autoimmune nephritis, compared to MD88+/- MRL/lpr mice." (PMID 36389822, 2022). "Our data advocates for a scenario in which the worsening of autoimmunity in MyD88–/–Aire–/– mice could be caused by the lack of MyD88 signaling in mTECshigh, downregulation of their chemokines needed to recruit CD14+moDCs and, consequently, suboptimal production of thymic Tregs." (PMID 32398640, 2020). "The ABIN1 mutation-induced autoimmunity is suppressed by crossing with MyD88 knockout mice, suggesting that the suppression of TLR-MyD88 signaling by ABIN1 is needed for the phenotype to develop." (PMID 39996775, 2025). "Our data indicate that B cell-intrinsic iOPN can prevent the exacerbation of autoimmunity-driven B cell proliferation and activation, through the impairment of MYD88 signaling cascade." (PMID 36503430, 2022). "The importance of TLR/MyD88 signaling in Aire-dependent autoimmunity was suggested in experiments conducted with MyD88–/–Aire–/– double-knockout mice." (PMID 32398640, 2020). "These mice develop more severe symptoms of autoimmunity than Aire–/– single KO animals indicating the positive regulatory role of MyD88 signals in tolerance induction." (PMID 32398640, 2020). "The effects of MyD88-mediated signaling on lymphocytes, especially B cells, in autoimmunity have been documented; therefore, we focused on the lymphoproliferation-independent mechanism." (PMID 30250175, 2018). "We previously showed that MOG35-55/CFA immunization in MyD88−/− mice induces autoimmune T cells that actively downregulate adoptively transferred encephalitogenic T cells; this suggests that inhibition of MyD88 can generate protective autoimmunity." (PMID 28611775, 2017). "We showed previously that autoimmunity in ABIN1[D485N] mice is prevented by crossing them to MyD88-KO mice, establishing that hyperactivation of the MyD88 signaling network underlies the disease." (PMID 27807192, 2016). "We showed previously that autoimmunity in ABIN1[D485N] mice is prevented by crossing to MyD88-KO mice." (PMID 27807192, 2016). "Since soluble Bgn and Dcn are potent inflammatory modulators that activate Myd88-dependent TLRs in the context of autoimmunity, we sought to determine whether circulating Bgn and Dcn were altered in pSS." (PMID 34381449, 2021). "Thus, dysregulated Myd88 signaling in B cells plays an essential role in autoantibody production in autoimmunity, including pSS." (PMID 34381449, 2021). "Various studies suggested an important role for MyD88 in the induction of autoimmunity." (PMID 29522531, 2018). "It has been shown that both B-cell-specific MyD88 expression and T cells are essential for IgG2a/c anti-dsDNA autoantibody production in Lyn−/− mice, and conditional deletion of Lyn in B cells is sufficient for autoimmunity." (PMID 29521626, 2018). "The impact of MyD88 and IRAK1 deficiency on autoimmunity has been quite well documented." (PMID 20981241, 2010).
Autoimmunity (continued). "Some have suggested that Th1-mediated autoimmunity could be mediated through MyD88 activation, a common signal transduction protein used by most TLRs." (PMID 19094215, 2008). "Thus, long-term repeated stimulation of bacterial products may induce breakdown of B cell tolerance as shown in previous studies that altered BCR and microbial TLR signals (e.g., TLR4 and MyD88) may promote the breakdown of autoimmunity." (PMID 37027536, 2023). "Additionally, zonulin secretion was regarded as MyD88-dependent followed by protein ZO-1 dissociation from the tight junctional complex, which was responsible for both intestinal and extraintestinal inflammation, autoimmunity, and cancer." (PMID 38264043, 2023). "However, since spontaneous EAE develops normally in MyD88−/−, PLP-TCR transgenic mice, adjuvants may be required to induce MyD88-independent signaling that can regulate autoimmunity." (PMID 28611775, 2017). "Downstream of TLRs, the adaptor proteins MyD88 and CARD9 and the transcription factor IRF5 generate hyperactivated signaling in LynKO myeloid cells and drive autoimmunity in LynKO mice." (PMID 37265689, 2023). "Our earlier studies had shown that autoimmunity and glomerulonephritis in ABIN1[D485N] mice were prevented by crossing to MyD88 KO mice or mice expressing kinase-inactive mutants of IRAK4 or IRAK1." (PMID 31694920, 2019). "To gain mechanistic insights on the roles of MyD88 and TRIF in the development of autoimmunity in this model, we focused on MyD88CD11c-KO and TRIFCD11c-KO mice." (PMID 29522531, 2018). "By contrast, in pristane-induced autoimmunity, TLR/MyD88 signaling, leading to type I IFN and proinflammatory cytokines, does not require DCs, but rather immature monocytes." (PMID 23557436, 2013). "MYD88 and NFKB1, central to toll-like receptor and NF-kB signaling, are therapeutic targets in cancer and autoimmunity, with inhibitors and antibodies that could be repurposed for NDs." (PMID 41153395, 2025). "In contrast to MyD88, the role of the TRIF-mediated branch of TLR signaling in autoimmunity is less studied, with existing evidence suggesting that TRIF-mediated signaling protects against autoimmunity." (PMID 29522531, 2018). "IgM plasma cell expansion is temporally and genetically separable from autoimmunity in Lyn−/− mice; this phenotype develops in mice as young as 7–10 weeks of age with 100% penetrance, is B-cell intrinsic, and is not dependent upon MyD88 expression." (PMID 29521626, 2018). "There is mounting evidence documenting that the crippling of this pathway at the level of TLR, MyD88, or IRAK1/4 may confer therapeutic efficacy in autoimmunity and auto-inflammatory diseases." (PMID 20981241, 2010). "However, MyD88 is expressed in many immune and non-immune cell types, and can contribute to autoimmunity at multiple points during disease development." (PMID 29930295, 2018).
melanoma (38 papers, 2010 to 2025). A malignant, usually aggressive tumor composed of atypical, neoplastic melanocytes. "Here we show that IRAK-M, a negative regulator of MyD88 signaling, is deficient or low in melanoma and expression levels correlate with patient survival." (PMID 32533049, 2020). "Thus, our study contributes to a better understanding of the immune mechanisms involved in BCG immunotherapy in murine melanoma and support future approaches including the use of MyD88-related agonists associated with BCG to improve cancer immunotherapy." (PMID 38835781, 2024). "Moreover, the MyD88/IL-1R axis, downstream of IL-1 signaling, has been demonstrated to regulate PD-1/PD-L1 expression in melanoma-associated immune cells, again in line with the PD-1/PD-L1 expression in RDEB mouse immune cells." (PMID 37809094, 2023). "In addition, the expression of myeloid differentiation factor 88 (MyD88), a key adapter molecule of the TLRs signaling pathway, and melanoma differentiation-associated gene 5 (MDA5) was measured." (PMID 29312337, 2017). "Critically, the effects of LTX-315 on DCs the consequent promotion of anti-melanoma immunity depend on the cytosolic signal transducer myeloid differentiation response gene 88 (MyD88)." (PMID 38545099, 2024). "In summary, MyD88 signaling showed to be an important pathway on BCG immunotherapy to ensure melanoma control in mice, raising future possibilities for the development of agonists or recombinant BCG to improve cancer immunotherapy." (PMID 38835781, 2024). "In line with this notion, LTX-315-induced maturation and dLN homing of TiDCs was diminished in B16 melanoma-bearing MyD88-/- mice." (PMID 38545099, 2024). "In this study, we showed that MyD88 is an important molecule in BCG-mediated antitumor response against melanoma." (PMID 38835781, 2024). "Taken together with the immune cells infiltrated in the TME, the M1-like macrophages polarization only in WT reinforce the importance of MyD88 signaling for the recruitment of inflammatory cells leading to the efficient melanoma growth control." (PMID 38835781, 2024). "In order to confirm the relevance of MyD88 signaling for BCG immunotherapy against melanoma, we developed a co-culture strategy simulating the interactions that probably occurs between BCG-infected tumor cells and the infiltrated immune cells in the TME." (PMID 38835781, 2024). "Taken together, our results demonstrate the fundamental role of MyD88 in the BCG antitumor response against murine melanoma." (PMID 38835781, 2024). "Taken together, our data summarized in the graphical abstract demonstrate that MyD88 molecule is crucial to induce an efficient BCG-antitumor response to control murine melanoma." (PMID 38835781, 2024). "Then, we performed a flow cytometry assay to evaluate the immune cells infiltrated in melanoma from WT and MyD88-/-." (PMID 38835781, 2024). "(I and J) Comparison of tumor growth and survival curves of B16 melanoma between MyD8−/− (n = 9) and MyD88−/−;Cd300a−/− mice (n = 10) after inoculation of B16 melanoma." (PMID 34751648, 2021). "The observation that knockdown of MYD88 abolishes MPLAs-enhanced STAT3 phosphorylation suggests that TRIF can be regulated by MYD88 in melanoma." (PMID 32312954, 2020). "We can collect additional patient melanoma samples to study the roles of gene polymorphisms of TLR4, MYD88, TRIF, and STAT3 in melanomagenesis in the future." (PMID 32312954, 2020). "We investigated the protein expression profiles of MyD88 signaling inhibitors in melanoma cell lines and melanocytes; IRAK-M was consistently low or deficient in most melanoma lines." (PMID 32533049, 2020). "Considering the link between IL-1R/MyD88-mediated inflammation and tumor progression, we investigated the expression profiles of numerous molecules known to inhibit MyD88 signaling in melanoma using data from Cancer Cell Line Encyclopedia (CCLE)." (PMID 32533049, 2020).